MCL1 (MCL1 apoptosis regulator, BCL2 family member)
Diseases named in the same sentence as MCL1 in open-access papers (continued):
Sharing a sentence is not in itself a finding about the gene and the disease.
melanoma (continued). "To examine the effects of Mcl-1 knockdown and ABT-737 on melanoma in vitro, we used six melanoma cell lines: Lox IMVI, Malme-3M, MeWo, SK-MEL-2, SK-MEL-5 and SK-MEL-28." (PMID 19684859, 2009). "Moreover, the Mcl-1 specific inhibitor, S63845, potentiated the efficacy of DT2216 in melanoma cells in which DT2216 determined an increase of Mcl-1 protein." (PMID 41501884, 2026). "MCL1, regulated by survival pathways like PI3K/AKT and ERK, is frequently amplified in solid tumors (e.g., non-small cell lung cancer (NSCLC), breast cancer, melanoma) and hematologic malignancies, playing a key role in therapy resistance." (PMID 41155156, 2025). "Importantly, combinations of BH3 mimetics with Mcl-1 inhibitors, namely SC-2001, S63845, and S64315 (MIK655), are even more effective at eradicating melanoma in vitro and in vivo." (PMID 40721981, 2025). "Another key anti-apoptotic protein, Mcl-1, plays a particularly important role in BRAF-mutant melanomas; in these tumors, MAPK pathway hyperactivation drives both increased MCL1 transcription and stabilization of Mcl-1 protein through phosphorylation at threonine 163, preventing its degradation." (PMID 40721981, 2025). "This MCL-1 dependence was driven by a significant downregulation of the sensitizer NOXA, which frees MCL-1 after treatment with ALK-TKIs to block therapy-induced apoptosis, as previously demonstrated in other solid tumors such as melanoma and rhabdomyosarcoma." (PMID 40113795, 2025). "Upregulation of Sestrin 2- but not Sestrin 3- by MCL1 depletion was observed in a panel of melanoma cell lines, arguing for the generalization of this effect in melanoma cells." (PMID 41326406, 2025). "Although there is a great potential to treat melanoma with MCL1 inhibitors in combination with ICIs, the current generation of MCL1 inhibitors are not suitable for use in the clinic due to dose-dependent cardiac toxicity." (PMID 38459020, 2024). "While the feasibility of using MCL1 inhibitors to target melanoma has been shown, previous studies have not investigated the effects of the MCL1 inhibitor on immune cells." (PMID 38459020, 2024). "With the goal of improving the therapeutic effectiveness, and overcoming drug resistance in melanoma, we combined vemurafenib, as well as SCH772984 with the Mcl-1 inhibitor S63845, and report here strongly enhanced effects on cell viability, apoptosis, and on proapoptotic pathways." (PMID 36902392, 2023). "We observed that different melanoma cells, surviving after RU486 treatment, down regulated expression of different Bcl-2-related pro-death genes (i.e., bax, bak, bid), whereas upregulated anti-death bcl-xl and mcl-1." (PMID 36766760, 2023). "In melanoma cells, PG could bind to the BH3 domain and activate the mitochondrial apoptosis pathway by disrupting the McL-1/BAK complex, an anti-apoptotic member of the Bcl-2 family." (PMID 36364107, 2022). "Concordantly with the gene modulation results, a significant reduction in miR-214-3p, targeting BAX, and a significant up-regulation of miR-16-5p, targeting BCL2 and BIRC5, and of miR-193a-3p, targeting MCL-1, were observed in PEL and EPI -treated melanoma cells." (PMID 35877720, 2022). "Combination targeting MCL-1 and BCL-XL synergistically killed melanoma cell lines in vitro." (PMID 35201512, 2022). "Additionally, the MCL1 gene, a member of the BCL2 family of anti-apoptotic proteins that promotes apoptosis activation via mitochondrial pathways in C32 melanoma cells, inhibits apoptosis in a variety of cancers Bak and Bax pro-apoptotic proteins." (PMID 35547125, 2022). "In a separate study, CRISPR/Cas9 mediated knockout of BFL-1 in melanoma cells were not sensitized to pharmacological inhibition of MCL-1, BCL-XL, and BCL-2 indicating that the melanoma cells do not rely on BFL-1 for survival." (PMID 35201512, 2022).
melanoma (continued). "Additionally, Mcl1-specific MIM1 was identified in a stapled peptide-based screen, which showed good efficacy as a monotherapy against colo-829 melanoma cells, and which synergized the death inducing effects of ABT-737 or Decarbazine." (PMID 34753495, 2021). "Mcl-1 was highly expressed in MeWo and Mel-HO cells and silencing it significantly increased AdV-TRAIL-induced cytotoxicity and made both AdV-TRAIL-infected melanoma cell lines more sensitive to TRAIL-induced apoptosis." (PMID 34028599, 2021). "Since we did not observe changes in the expression of the validated miR-29 targets AKT3, MCL1, and DNMT3B, we identified new targets whose repression may contribute to restricting melanoma development." (PMID 33808771, 2021). "Using a combination of cell viability assay, BCL2 family knockdown cell lines, live cell imaging, and sphere formation assay, we found that combining inhibition of MCL1, an anti-apoptotic BCL2 protein, with azacitidine had substantial pro-apoptotic effects in multiple melanoma cell lines." (PMID 34451846, 2021). "In addition, computer-designed Mcl-1 inhibitors shall be used to establish strategies for Mcl-1 silencing and enhancement of the oncolytic activity of TRAIL-“armed” oAds in melanoma." (PMID 34452286, 2021). "To investigate whether Mcl-1 silencing can overcome AdV-TRAIL resistance, we initially examined four melanoma cell lines (MeWo, Mel-2a, SK-Mel-19, Mel-HO) for their sensitivity to TRAIL/AdV-TRAIL." (PMID 34028599, 2021). "S63845 is a myeloid leukemia cell differentiation protein 1 (MCL1) inhibitor with therapeutic efficacy against a large number of melanoma cell lines, excluding a few that are not affected by MCL1 inhibition." (PMID 34540687, 2021). "It is noteworthy that the combination of MCL1 inhibitors with AZA is currently in clinical trials for hematological cancers, which will likely provide useful information and help in moving this combination to clinical trials for melanoma patients quickly." (PMID 34451846, 2021). "In this regard, we found that transiently expressed miR-193b as well as anti-Mcl-1 artificial microRNAs and small hairpin RNAs are able to suppress Mcl-1 in melanoma cells (results not shown)." (PMID 34028599, 2021). "Interestingly, these combinations had similar effects in most cases, indicating that MCL1 and BCLXL are essential BCL2 family members for melanoma survival." (PMID 32513939, 2020). "These combinations kill melanoma cells, regardless of their mutation status in BRAF or NRAS, likely because MCL1 and BCLXL are downstream of these common mutations." (PMID 32513939, 2020). "In summary, our data strongly indicate that combination treatment targeting both MCL1 and BCLXL may provide a new and novel therapeutic option for patients with advanced melanoma." (PMID 32513939, 2020). "Previously published work has shown that single agent BH3 mimetics are not effective alone for melanoma, and that MCL1 is an essential anti-apoptotic protein." (PMID 32764384, 2020). "The study of Bcl-2 proteins in melanoma followed the same trend and also focused on BCL2, Bcl-xL, and MCL1 although, to our knowledge, a comprehensive study of the relative expression of all six anti-apoptotic Bcl-2 proteins in melanoma cells or tumors has not been performed yet." (PMID 33396645, 2020). "In addition, MCL1 and BCLXL can be induced as part of the adaptive response in melanoma cells to various triggers, including targeted therapies." (PMID 32513939, 2020). "Our data show for the first time that therapies targeting specific combinations of BCL-2 pro-survival proteins, namely MCL-1 plus BCL-XL and MCL-1 plus BCL-2, could have significant benefit for the treatment of melanoma." (PMID 31019203, 2019). "Hence, BH3-mimetic combinations, particularly those targeting MCL-1 plus BCL-XL, result in melanoma cell apoptosis." (PMID 31019203, 2019).
melanoma (continued). "To test the hypothesis that BRAF/MEK inhibitors could sensitize melanoma cells to MCL-1 inhibitors, we compared the effects of A1210477 given before versus after BRAF inhibitor treatment in A375M melanoma cells." (PMID 31727958, 2019). "In melanoma resistant to BRAFi and MEKi, in particular BH3-mimetics targeting MCL-1 and manipulation of the MCL-1/NOXA-axis maybe beneficial and warrant clinical testing." (PMID 29794999, 2018). "This study reveals opposed effects of miR-193b / miR-30c-1* and miR-576-5p, respectively, on melanoma cell invasion and on expression of BCL9 and MCL1, possibly accounting for the contrasting invasive phenotypes observed in A375 cells transfected with these miRNAs." (PMID 30197759, 2018). "Due to their potential to induce apoptosis in melanoma cells by increasing NOXA and AIF and decreasing MCL-1 levels, EZH2 inhibitors may enhance the sensitivity to MAPK inhibition in combination regimens with BRAFi and MEKi." (PMID 29794999, 2018). "Many studies, including ours, have shown that targeting single anti-apoptotic BCL-2 family members is not sufficient to treat melanoma, and that targeting both MCL-1 and BCL-2 is needed to eliminate the MIC population." (PMID 27086916, 2017). "The mode of the response to parthenolide is bound to the molecular characteristics of melanoma cells, particularly to the basal MITF-M expression level but other cell-autonomous differences such as NF-κB activity and MCL-1 level might also contribute." (PMID 26824319, 2016). "We posit that MCL-1 inhibition via miR-32 or sabutoclax can be effective therapy, alone or in combination with other agents, in a variety of human melanoma subtypes that currently have no effective treatment options available in the clinic." (PMID 27846237, 2016). "One of the studies indicate that combining ABT-737 with 4-HPR (an indirect MCL-1 inhibitor) is effective in killing both the bulk of melanoma cells and MICs, but not normal melanocytes." (PMID 27829238, 2016). "Chetoui’s group demonstrated that Mcl-1, an anti-apoptotic protein from the Bcl-2 family that is regulated by extracellular signal-regulated kinases (ERK) signaling pathway, contributes significantly to the drug resistance of melanoma cells." (PMID 27658583, 2016). "BCL-2 inhibitors have been successful in treatment of chronic lymphocytic leukemia, but not in melanoma due to high expression of anti-apoptotic proteins such as MCL-1." (PMID 27829238, 2016). "We observed an inverse correlation between expression of CDKN2A gene transcripts and MCL-1 transcripts in human melanoma clinical samples (INK4a and ARF are not separable in this analysis)." (PMID 27846237, 2016). "Treatment of B-RafV600E/PTEN-null melanoma cells with the B-Raf inhibitor vemurafenib led to increased fibronectin expression that abrogates the therapeutic response due to enhanced PI3K-Akt signaling and Mcl-1 expression." (PMID 26405162, 2015). "In the present study, we have shown that originally these patient-derived melanoma populations exhibit variable expression of pro-survival genes from the BCL-2 family and inhibitors of apoptosis (IAPs), and differ in the baseline MCL-1 transcript stability as well." (PMID 26035829, 2015). "Those melanomas in which microenvironment-driven changes in MCL-1 level were not substantial involved an increase in BCL-XL expression as a complementary alteration." (PMID 26035829, 2015). "Additionally, ABT-737 in combination with the BRAF inhibitor PLX4720 showed augmentation of apoptosis in BRAF mutant melanoma cell lines that was BIM dependent and mediated through an enhancement of the BIM:MCL-1 interaction." (PMID 24983357, 2014). "Unfortunately, melanoma cells are insensitive to single ABT-737 treatment, and Mcl-1 might have a major role in this resistance." (PMID 24920406, 2014). "Data have previously shown that melanoma cells do not undergo apoptosis following MEK inhibitor treatment as a result of constitutively high Mcl-1 expression levels." (PMID 23527225, 2013).
melanoma (continued). "We investigated the extent to which Mcl-1 affects the sensitivity of melanoma cells to ABT-737 and thus whether combination therapy targeting Mcl-1 and Bcl-2 has a promise in the context of melanoma." (PMID 24223823, 2013). "In this study, we systematically investigated the relevance of antiapoptotic Bcl-2 proteins, i.e., Bcl-2, Bcl-xL, Bcl-w, Mcl-1, and A1, in melanoma cell lines and non-malignant cells using RNAi." (PMID 22292048, 2012). "This indicates that – in contrast to non-malignant cells - melanoma cells require the presence of Mcl-1 or A1 for survival." (PMID 22292048, 2012). "We previously found that resistance to ABT-737 in melanoma cells is mediated by the anti-apoptotic Bcl-2 member Mcl-1, which ABT-737 does not inhibit." (PMID 21897876, 2011). "Given the dramatic caspase-8 and Bid cleavage observed following treatment with Mcl-1 DsiRNA and ABT-737 in melanoma, we investigated whether expression of either protein correlates with combination treatment response." (PMID 19684859, 2009). "Based on our previous results, non-sun exposed melanomas, such as uveal and mucosal melanomas, may be good candidates for treatment with MCL1 inhibitors." (PMID 38459020, 2024). "Since MCL-1 acts as a master regulator of apoptosis in various human malignancies, including melanoma, it is not excluded that a decrease in MCL-1 in WM266.4 cells with RIPK4 silencing may affect their susceptibility to BRAFi." (PMID 36765875, 2023). "Consistently, in various cultured cancer cells (including melanoma, sarcoma, hematologic, and epithelial cancer cells), this “citrate strategy” efficiently inhibits the IGFR1/AKT pathway, promotes PTEN activity, reduces Bcl-xL and MCL1 expression, and increases sensitivity to standard chemotherapy." (PMID 35626081, 2022). "miR-29 may elicit its tumor suppressive potential by repressing targets such as AKT3, DNMT3A/B, or MCL1; however, miR-29 hairpin inhibitors failed to increase the expression of these validated targets in A375 melanoma cells." (PMID 33808771, 2021). "We demonstrate here that the lack of efficacy of this combination in melanoma may be due to their dependence on MCL1, rather than BCL2 for survival." (PMID 34451846, 2021). "For example, MCL-1 inhibitors (e.g., S63845 or AMG 176) have been combined with inhibitors against MEK, HER-2, B-RAF or EGFR and shown to induce a cytotoxic response in solid tumours such as breast, non-small cell lung cancer, lung adenocarcinoma and melanoma cells." (PMID 33799592, 2021). "We found that knockdown of MCL1, and to a lesser extent BCLXL, sensitized cells to treatment with AZA up to a dose of 2.5 uM, indicating that a combination of MCL1 or BCLXL inhibition with AZA treatment may be an effective combination in melanoma." (PMID 34451846, 2021). "Regarding A-1155463, while it did not affect melanoma cell viability, it increased the effect of immunotoxin targeting the melanoma-associated chondroitin sulfate proteoglycan 4 (CSPG4) when combined with the Mcl-1 specific inhibitor, S63845." (PMID 33803452, 2021). "Notably, combinations targeting both MCL-1 and BCL-2 (e.g., S63845 and Venetoclax) have proven efficacious and safe in clinical trials in both haematological (e.g., AML, T-cell ALL, MCL) and solid cancers (e.g., melanoma)." (PMID 33799592, 2021). "In addition, among the genes indirectly regulated by miR-146a through NFkB activity, we found CCL2, IL6, and VEGFA, which contribute to the proinflammatory phenotype, CD274 (PDL1), which promotes melanoma cell proliferation, and BCL2L1 and MCL1 antiapoptotic genes." (PMID 32967672, 2020). "Summarizing, presented data indicate that blocking of Mcl-1 protein may be a potential important target in malignant melanoma treatment, and may constitute the basis for further in vitro studies with the use of MIM1 as the new anti-melanoma agent." (PMID 31432325, 2020).
melanoma (continued). "Therefore, melanoma tumour cells are not dependent on MCL1 for survival per se; rather they are dependent on MCL1, to a far greater extent than the other pro-survivals, when the ERK1/2 pathway is inhibited." (PMID 31727888, 2019). "Hence, melanoma cells are not exclusively dependent on BCL-2, BCL-XL, or MCL-1 for survival, nor does co-targeting BCL-2, BCL-XL and BCL-W cause significant melanoma cell killing." (PMID 31019203, 2019). "In melanoma and other tumors, resistance to kinase inhibitors like BRAFi and MEKi is often mediated by an abrogation of intrinsic apoptosis signaling pathways—namely by downregulation of BH3-only proteins or by induction and activation of BCL-2 family members like BCL-2, BCL-XL, BFL-1, and MCL-1." (PMID 29794999, 2018). "The data also suggest that melanoma’s recalcitrance to many forms of therapy may lie, at least in part, in its ability to circumvent apoptosis by downregulating ARF/miR-32 and/or upregulating MCL-1." (PMID 27846237, 2016). "We here identify miR-32/MCL-1 pathway members as key early genetic events driving melanoma progression, and suggest that their inhibition may be an effective anti-melanoma strategy irrespective of NRAS, BRAF, and PTEN status." (PMID 27846237, 2016). "Our results suggest that EGb761 with or without in combination with targeting Mcl-1 may be a useful strategy in the treatment of melanoma." (PMID 25860257, 2015). "Our data would predict that a similar differential imbalance between pro (Bax)-/anti (Bcl-2, Bcl-xL, Mcl-1, Xiap)-apoptotic proteins is likely to occur within the subset of TAA-specific (but not bulk or viral-specific) CD4+ T cells in the peripheral blood of melanoma or RCC patients with AD." (PMID 25325015, 2014). "In contrast to 1205Lu melanoma cells, in primary fibroblasts no reduction of cell viability and no increase in cell death was observed on day 6, neither by inhibition of A1, Mcl-1, or A1/Mcl-1 alone nor by co-administration of 5-FU." (PMID 22292048, 2012). "Interestingly, in our study inhibition of Mcl-1 and A1 efficiently induced cell death in a panel of melanoma cell lines without additional stimulus." (PMID 22292048, 2012). "We found that melanoma cells required the presence of specific antiapoptotic Bcl-2 proteins: Inhibition of Mcl-1 and A1 strongly induced cell death in some melanoma cell lines, whereas non-malignant cells, i.e., primary human fibroblasts or keratinocytes were not affected." (PMID 22292048, 2012). "As 9.2.27PE lead to rapid decrease in Mcl-1 protein levels, this lead us to investigate whether knockdown of Mcl-1 protein expression could increase the [Ca2+]i levels, decrease the Δψm and decrease the cell viability in ABT-737 treated melanoma cells." (PMID 21915275, 2011). "Thus, strong and frequent CTL responses against Mcl-1 were detected in CLL patients, melanoma patients, pancreatic cancer patients and breast cancer patients, whereas no responses could be detected in healthy individuals." (PMID 21304176, 2010). "However, we report that reduction of Mcl-1 expression alone is not enough to significantly reduce survival in multiple melanoma cell lines." (PMID 19684859, 2009). "Also, betulinic acid triggered upregulation of Mcl-1, another anti-apoptotic Bcl-2 family protein, in melanoma cells, whereas no changes in Mcl-1 levels were detected in squamous cell carcinoma cells." (PMID 19325847, 2008). "The alterations in the levels of proteins impacting the MCL-1 activity and stability, such as p-ERK1/2, BIM and NOXA, could explain the differences in pro-apoptotic response to MCL-1 inhibitors between trametinib-resistant melanoma cells grown with and without trametinib." (PMID 37835493, 2023). "Additionally, due to gamma-secretase and B-cell lymphoma 2 (Bcl-2) expression of melanoma CSCs, correlated with that of ALDH, the administration of their inhibitors, i.e., gamma-secretase inhibitors (GSI) and myeloid cell leukaemia sequence 1 (MCL-1)—an inhibitor of Bcl-2—is targeting CSCs." (PMID 35334544, 2022).